PPA1 (inorganic pyrophosphatase 1)
Diseases named in the same sentence as PPA1 in open-access papers (continued):
Sharing a sentence is not in itself a finding about the gene and the disease.
tumor (continued). "As proliferation was one of the key elements of tumor progression, next we investigated the function of PPA1 in NSCLC cell proliferation." (PMID 31551407, 2019). "Altogether, these findings suggested that JNK activation was responsible for PPA1-mediated NSCLC tumor progression in vitro." (PMID 31551407, 2019). "Since PPA1 contributes to the NSCLC tumor progression via promoting cell proliferation and inhibiting cell apoptosis in vitro, we next tested the results in a xenograft animal model." (PMID 31551407, 2019). "Consistently, IHC results revealed the distinct expression patterns of PPA1 among tumor tissues from different patients, with immunostaining mainly located in cytoplasm." (PMID 28938583, 2017). "RT-qPCR results showed that PPA1 mRNA level in tumor tissues was higher than that in adjacent normal tissues (P=0.005)." (PMID 28938583, 2017). "Meanwhile, Western Blot identified the specificity of PPA1 antibody with a single band of the expected size (33kD) in this study, and showed that PPA1 was up-regulated in tumor tissues." (PMID 28938583, 2017). "In short, PPA1 expression was found to be positively correlated with increased tumor malignancy (p<0.01)." (PMID 29100310, 2017). "Conversely, xenografted tumor tissues from the shPPA1-2 group expressing low levels of PPA1 exhibited a strong E-cadherin and weak Vimentin expression profile." (PMID 29100310, 2017). "Cell proliferation and apoptosis assays were used to investigate PPA1‐regulated cell growth in tumor cells." (PMID 27666431, 2016). "To further understand the expression of PPA1 in other tumor types, we used PPA1 monoclonal antibodies to test PPA1 expression in 675 cases of tumor tissues, which comprised 12 different types of tumors, and 305 cases of nontumor tissues." (PMID 27666431, 2016). "The tumor suppressive function of PPA1 presented above seems contradictory to the observed elevated levels of the protein in the N(+) tumors." (PMID 26948660, 2016). "To further investigate the function of PPA1 involvement in tumor cell apoptosis, we established ES2‐, OVCAR3‐, H460‐, and H1299‐PPA1 knockdown cell lines." (PMID 27666431, 2016). "On the other hand, certain tumor cells have been reported to enrich their surrounding environment with lactic acid generated by fermentation (the Warburg effect), while upregulating the expression of PPA1." (PMID 40005593, 2025). "Inorganic PPA1 is associated with a variety of tumor progression, but no relevant studies have been found in psychiatric and neurological diseases." (PMID 38664915, 2024). "Because of its remarkable role in tumor development, PPA1 may serve as a biological target for adjuvant therapy of tumor malignancies." (PMID 36505776, 2022). "Furthermore, PPA1 has been shown to play a vital role in mediating tumor proliferation, apoptosis, and metastasis in a JNK activation-dependent or -independent manner; this is discussed in detail below." (PMID 36505776, 2022). "The higher the grade and stage of the tumor tissue, the higher the PPA1 expression." (PMID 36505776, 2022). "Role of inorganic pyrophosphatase (PPA1) in tumor progression." (PMID 36505776, 2022). "In addition, we observed that more PPA1-upregulated cells metastasized to the lung and initiated secondary tumor, which was also rescued by the PI3K inhibitor." (PMID 34595179, 2021). "We verified that ectopic PPA1 significantly promoted tumor growth, which could be reversed by the PI3K inhibitor." (PMID 34595179, 2021). "We are working on PPA1 targeting nanoparticles, which could deliver various kinds of drugs to tumor tissues." (PMID 34858817, 2021). "Therefore, PPA1 appears as an outstanding tumor-targeting modification of synergistic drug conjugate for effective anti-tumor treatment." (PMID 34858817, 2021).
tumor (continued). "Inorganic pyrophosphatase (PPA1) promotes tumor progression in several tumor types." (PMID 31551407, 2019). "Fourth, tumor metastasis was inhibited after PPA1 was silenced in vivo." (PMID 29100310, 2017). "After we showed that PPA1 is up‐regulated in tumor tissues, we determined whether the observations in clinical samples were also seen in tumor cell lines." (PMID 27666431, 2016). "Thus, PPA1 is most likely involved in tumor metastasis by promoting EMT." (PMID 36505776, 2022). "In LGG, pathways associated with a good prognosis include oxidative phosphorylation (LHPP, PPA1, CYC1), supported by a high WWOX/HIF1A ratio, which improves energy metabolism and reduces tumour aggressiveness." (PMID 41007296, 2025). "In this study, we identified a novel mechanism by which PPA1 selectively up-regulates the expression of the EMT master regulator Slug to drive EMT and enhance tumor metastasis." (PMID 34595179, 2021). "PPA1-DOX construct showed high binding affinity with PD-L1 in vitro and specifically enriched within tumor when administered in vivo." (PMID 34858817, 2021). "By contrast, PPA1-DOX and free PPA1 exhibit rather low toxicity to major organs of tumor-bearing mice." (PMID 34858817, 2021). "We found that PPA1-DOX construct showed high binding affinity with PD-L1 in vitro and was specifically enriched within tumor when administered in vivo." (PMID 34858817, 2021). "To investigate this role of PPA1 in NSCLC tumor progression, we first checked the phosphorylation of JNK in PPA1-interferd H460 cells." (PMID 31551407, 2019). "In our present study, we further revealed that PPA1 promotes JNK dephosphorylation, eventually leading to NSCLC tumor progression, indicating the tumor suppressor role of JNK in PPA1-mediated NSCLC progression." (PMID 31551407, 2019). "We investigated the expression of PPA1, E-cadherin, and Vimentin in xenografted mouse EOC tumor slices." (PMID 29100310, 2017). "Proteins important for tumor cell survival (SND1), proteins known to be expressed by MM cells (PPA1, CCT3, NME1, SPAG9), and a marker for bone resorption (DPYD) were detected at higher levels in the NBM coculture supernatants." (PMID 26545722, 2015). "This study identifies PPA1 as a novel metabolic dependency in CRC, offering a strategic target for disrupting tumor survival under glucose-limited conditions characteristic of the tumor microenvironment." (PMID 41315223, 2025). "Immunohistochemical staining detected PPA1 expression in 305 noncancerous tissues and 675 tumor tissues, which included 12 different tumor types." (PMID 27666431, 2016). "As a result, PPA1-DOX conjugate was found to exhibit a significantly lower toxicity to non-tumor cells, in particular for cardiomyocytes and hepatocytes that are major toxic targets of DOX, and a remarkably higher antitumor activity in vivo, as compared with DOX and free PPA1, respectively." (PMID 34858817, 2021). "There was no statistical correlation between PPA1 expression and gender, age, serum CEA, tumor location, tumor differentiation, tumor size or tumor invasion depth (P>0.05)." (PMID 28938583, 2017).
infection (6 papers, 2017 to 2024). The state of being infected such as from the introduction of a foreign agent such as serum, vaccine, antigenic substance or organism. "OPDA, PPA1 and other phytoprostanes accumulate after infection with necrotrophic pathogens independent of JA." (PMID 28207847, 2017).
benign tumor (1 paper, 2017). "Compared to normal ovarian tissues and benign tumor tissues, PPA1 was upregulated in EOC and borderline tumors (p<0.05)." (PMID 29100310, 2017). "IHC was performed to examine PPA1 expression in EOC (n=55), borderline tumors (n=20), benign tumors (n=24) and normal ovarian tissues (n=23)." (PMID 29100310, 2017). "We found that PPA1, which was expressed predominantly within cytoplasm, was generally weak or negative in both normal ovarian and benign tumor tissues." (PMID 29100310, 2017).
PPA1 also shares sentences with these, for which no sentence is quoted: hepatocellular carcinoma (3 papers); breast tumor (2); laryngeal squamous cell carcinoma (2); lung adenocarcinoma (2); lymph node metastases (2); prostate carcinoma (2); adenocarcinoma (1); bladder cancer (1); brain tumors (1); cardiomyopathies (1); colon adenocarcinoma (1); depression (1); diffuse large B-cell lymphoma (1); hyperthyroidism (1); Insulin resistance (1); invasive ductal carcinoma (1); laryngeal carcinoma (1); metabolic disorder (1); metastatic tumors (1); neurological diseases (1); nicotine dependence (1); pulmonary diseases (1); soft tissue tumors (1); squamous cell carcinoma of the (1); stomach cancer (1); thyroid cancer (1).